QRFP (pyroglutamylated RFamide peptide)
Description:
Stimulates feeding behavior, metabolic rate and locomotor activity and increases blood pressure. May have orexigenic activity. May promote aldosterone secretion by the adrenal gland (By similarity).
Synonyms: 26RFa; P518; prepro-26RFa
Tractability: Antibody: its Gene Ontology location is reachable by antibodies, with high confidence; UniProt places it where antibodies can reach, with medium confidence; UniProt predicts a signal peptide or a membrane-spanning region.
Target class: Secreted protein
Gene: Protein-coding gene on chromosome 9 (130,892,707 to 130,896,812, reverse strand). Ensembl gene ENSG00000188710.
Subcellular location: Secreted
Pathways (Reactome):
Signal Transduction: G alpha (q) signalling events; Orexin and neuropeptides FF and QRFP bind to their respective receptors
Gene Ontology:
Molecular function: neuropeptide hormone activity; orexigenic neuropeptide QRFP receptor binding; G protein-coupled receptor binding
Biological process: neuropeptide signaling pathway; locomotory behavior; positive regulation of blood pressure; regulation of feeding behavior; grooming behavior
Cellular component: extracellular region
Genetic constraint (gnomAD): Loss-of-function variants: 7 observed, 8.85 expected, observed/expected ratio (o/e) 0.79, 90% interval 0.45 to 1.47. That is too few expected variants to judge how well the gene tolerates losing a copy. Missense variants: 204 observed, 185.59 expected, observed/expected ratio (o/e) 1.1, 90% interval 0.98 to 1.23. Synonymous variants: 91 observed, 78.16 expected, observed/expected ratio (o/e) 1.16, 90% interval 0.98 to 1.39.
Homologues: Orthologues: chimpanzee QRFP (99% identical), macaque QRFP (88% identical), dog QRFP (67% identical), mouse Qrfp (62% identical), pig QRFP (60% identical), rat Qrfp (58% identical), guinea pig QRFP (57% identical), tropical clawed frog qrfp (44% identical).
Diseases named in the same sentence as QRFP in open-access papers:
QRFP is named in the same sentence as 3 diseases in open-access papers, as found by Europe PMC text mining. Sharing a sentence is not in itself a finding about the gene and the disease. The quoted sentences say what the papers report.
Anxiety (4 papers, 2016 to 2024). Intense feelings of nervousness, tension, or panic often arise in response to interpersonal stresses. "The anxiety-like behavior of QRFP-deficient mice confirmed these data." (PMID 38994950, 2024). "In fact, we also found that QRFP-deficient mice showed an anxiety-like phenotype." (PMID 27835635, 2016). "In fact, the previous animal studies using the elevated plus maze test showed an anxiolytic effect of 26RFa, while QRFP knock-out mice showed increased anxiety." (PMID 36831780, 2023). "The implication of QRFP peptides in stress behavior was proposed due to rich QRFPR1 and QRFPR2 mRNAs expression in rodent brain regions involved in stress and anxiety." (PMID 38994950, 2024).
prostate carcinoma (1 paper, 2023). A carcinoma that arises from epithelial cells of the prostate gland. "QRFPR, also named GPR103, activates glutamine RF−amide peptide (QRFP), is over-expressed in human prostate cancer, and stimulates the neuroendocrine differentiation and the migration of androgen-independent prostate cancer cells." (PMID 37025600, 2023).
QRFP also shares sentences with these, for which no sentence is quoted: colorectal cancer (1 paper).